SNX17 (sorting nexin 17)
Description:
Critical regulator of endosomal recycling of numerous surface proteins, including integrins, signaling receptor and channels. Binds to NPxY sequences in the cytoplasmic tails of target cargos. Associates with retriever and CCC complexes to prevent lysosomal degradation and promote cell surface recycling of numerous cargos such as integrins ITGB1, ITGB5 and their associated alpha subunits. Also required for maintenance of normal cell surface levels of APP and LRP1. Interacts with membranes containing phosphatidylinositol 3-phosphate (PtdIns(3P)).
Synonyms: KIAA0064
Tractability: Antibody: UniProt places it where antibodies can reach, with high confidence. PROTAC: ubiquitination databases record sites on it; its protein half-life has been measured.
Gene: Protein-coding gene on chromosome 2 (27,370,496 to 27,377,535, forward strand). Ensembl gene ENSG00000115234.
Subcellular location: Cytoplasm; Early endosome; Cytoplasmic vesicle membrane
Subcellular location (Human Protein Atlas): Vesicles; Cytosol
Gene Ontology:
Molecular function: low-density lipoprotein particle receptor binding; phosphatidylinositol binding; protein binding; signaling receptor binding
Biological process: endocytic recycling; cholesterol catabolic process; endosomal transport; intracellular protein transport; regulation of endocytosis; signal transduction; vesicle-mediated transport
Cellular component: cytoplasm; cytoplasmic vesicle; cytoplasmic vesicle membrane; cytosol; early endosome; endosome; endosome membrane; Golgi apparatus; protein-containing complex; membrane
Genetic constraint (gnomAD): Loss-of-function variants: 35 observed, 65.85 expected, observed/expected ratio (o/e) 0.53, 90% interval 0.41 to 0.7. The upper end of that interval is the gene's LOEUF score, 0.7, which puts it in group 2 of 6, group 1 being the genes least tolerant of losing a copy. Missense variants: 538 observed, 629.99 expected, observed/expected ratio (o/e) 0.85, 90% interval 0.8 to 0.92. Synonymous variants: 259 observed, 241.62 expected, observed/expected ratio (o/e) 1.07, 90% interval 0.97 to 1.19.
Homologues: Orthologues: chimpanzee SNX17 (99% identical), macaque SNX17 (99% identical), dog SNX17 (99% identical), pig SNX17 (99% identical), mouse Snx17 (99% identical), rabbit SNX17 (99% identical), guinea pig SNX17 (98% identical), rat Snx17 (95% identical), zebrafish snx17 (77% identical), tropical clawed frog snx17 (76% identical), Drosophila melanogaster Snx17 (42% identical), Caenorhabditis elegans snx-17 (29% identical). Paralogues in human: SNX31 (37% identical), SNX27 (22% identical).
Diseases named in the same sentence as SNX17 in open-access papers:
SNX17 is named in the same sentence as 26 diseases in open-access papers, as found by Europe PMC text mining. Sharing a sentence is not in itself a finding about the gene and the disease. The quoted sentences say what the papers report.
diabetes (3 papers, 2017 to 2023). "In the group enriched with diabetic patients (6 out of 9 patients), seven proteasome genes (PSME4, PSMA7, PSMB4, PSMB6, PSMC4, PSMD7 and PSMD8) and three genes previously associated with common diabetes (SNX17, PARK7/DJ-1 and ATP5B) were highly expressed." (PMID 32302349, 2020). "Adachi and Tsujimoto found that SNX17 directly interacted with FEEL-1/stabilin-1, which was implicated in the development of diabetes." (PMID 28744461, 2017).
Cirrhosis (2 papers, 2012 to 2025). A chronic disorder of the liver in which liver tissue becomes scarred and is partially replaced by regenerative nodules and fibrotic tissue resulting in loss of liver function. "The cytoskeleton (COMMD5, KRTAP19-5, LLGL1 and SNX17) related genes were down-regulated in cirrhosis (F4)." (PMID 22397681, 2012).
type 2 diabetes (2 papers, 2018 to 2020). "Through visualization of the most connected genes of this module, we identified SNX17, previously associated with glucose-homeostasis in muscle and adipose tissues of type 2 diabetic patients." (PMID 32302349, 2020). "In particular, two (GALNT2, SNX17) were also suggested to be associated with type 2 diabetes and obesity in previous studies." (PMID 30110382, 2018).
cholelithiasis (1 paper, 2025). The presence of crystallized deposits forming in the gallbladder or biliary tree, primarily composed of cholesterol, bilirubin, and bile. "Seven genes, including GCKR, SNX17, ABCG8, MARCH8, FUT2, APOH, and HNF1A, were revealed to be colocalized with the causal signal between sphingomyelin and cholelithiasis." (PMID 40428345, 2025).
ciliopathy (1 paper, 2019). A genetic disorder of the cellular cilia or the cilia anchoring structures, the basal bodies, or of ciliary function. "In our previous investigation of the role of SNX17 in Notch signaling, we noticed that knockdown of SNX17 led to ciliopathy-related defect in zebrafish." (PMID 31671755, 2019).
dyslipidemia (1 paper, 2018). "Interestingly, four of the top five significant genes (GALNT2, SNX17, CETP, LIPC) were regarded as dyslipidemia associated genes in the original GWAS study." (PMID 30110382, 2018).
gastric cancer (1 paper, 2025). A primary or metastatic malignant neoplasm involving the stomach. "Previous studies have shown that ITGB5 promotes SNX17-mediated endosomal recycling of transforming growth factor beta receptor type 2 (TGFBR2), which enhances gastric cancer metastasis." (PMID 40303303, 2025).
glioblastoma (1 paper, 2014). The most malignant astrocytic tumor (WHO grade IV). "SNX17 loss-of-function through over-expression of a dominant-negative mutant of SNX17 or siRNA knockdown of SNX17 in human glioblastoma U87 cells reduced steady-state APP levels and increased Aβ production." (PMID 25152012, 2014).
hepatocellular carcinoma (1 paper, 2025). A malignant tumor that arises from hepatocytes. "However, the role and mechanism of SNX17 in hepatocellular carcinoma (HCC) progression remain largely unknown." (PMID 40303303, 2025).
melanoma (1 paper, 2018). A malignant, usually aggressive tumor composed of atypical, neoplastic melanocytes. "Melanoma cells frequently exhibit phosphorylation of the corresponding serine of SNX12, SNX17, and SNX2137." (PMID 29520003, 2018).
myocardial infarction (1 paper, 2019). Gross necrosis of the myocardium, as a result of interruption of the blood supply to the area, as in coronary thrombosis. "Using miRanda we predicted that DQ593039 regulates the expression of the adaptor protein sorting nexin 17 (SNX17), which has been described to produce anti-arrhythmic effects by preserving functional SERCA2a protein in myocardial infarction." (PMID 31671920, 2019).
neuroblastoma (1 paper, 2014). Neuroblastoma (NB) is the most common solid, extracranial childhood tumor. "We also analyzed the effect of SNX17 knockdown in a neuronal cell type, the neuroblastoma cell line N2a." (PMID 24705369, 2014).
preeclampsia (1 paper, 2025). Preeclampsia is a hypertensive disorder of pregnancy that is characterized by new-onset hypertension with proteinuria presenting after 20 weeks of gestation, and depending on mild or severe forms may initially present with severe headache, visual disturbances, and hyperreflexia. "Thus, the mechanisms controlling PCSK9 and SNX17 under hypoxia and preeclampsia remain insufficiently understood and may have practical relevance for preventing fetal lipid imbalance and developing new therapeutic strategies in preeclampsia." (PMID 41446579, 2025).
viral infection (1 paper, 2018). "Moreover, SNX17 is a major cytosolic interacting partner of L2 and since L2 is able to shuttle between the cytoplasm and the nucleus due to the presence of NLS and NES it is possible this could modulate SNX17 normal function during the later stages of viral infection." (PMID 30181457, 2018).
infection (5 papers, 2015 to 2025). The state of being infected such as from the introduction of a foreign agent such as serum, vaccine, antigenic substance or organism. "It acts sequentially with SNX27, SNX4, and SNX17 along the recycling pathway in the process of the production and release of infection virions, suggesting that multiple membrane sources may contribute to the secondary envelopment of MCMV virions." (PMID 40299528, 2025). "Furthermore, we established an EAMG mouse model that overexpressed SNX17; the infection effect was good on the 21st day, along with a significant increase in SNX17 protein and mRNA expression levels in the gastrocnemius muscle tissue." (PMID 36311763, 2022). "SNX17 interacts with L2 early after infection, estimated about 2 to 9 h post-infection." (PMID 34683397, 2021). "However, knockdown of SNX27 only causes a marginal reduction in infection, but, interestingly, knockdown of both SNX17 and SNX27 results in significant reduction in infection, greater than the effect observed for SNX17 knockdown alone." (PMID 30181457, 2018). "In addition, a central segment of L2 binds SNX17, another cytoplasmic protein required for efficient infection, implying that this L2 segment is also accessible to the cytoplasm in some situations." (PMID 25693203, 2015).
cancer (4 papers, 2024 to 2025). A tumor composed of atypical neoplastic, often pleomorphic cells that invade other tissues. "However, the role and underlying mechanisms of SNX17 in human cancer, including HCC, remain poorly understood, and the function of SNX17 has not been fully elucidated." (PMID 40303303, 2025). "Moreover, phosphorylation at corresponding sites in SNX1, SNX3, SNX12, and SNX17 has been reported in various cancer types, hinting at a potential link between SNX phosphorylation and disease states." (PMID 40349777, 2025). "Moreover, many of these genes are shared across multiple cancer types, such as the pan-cancer 3′aTWAS gene sorting nexin 17 (SNX17), which plays a role in signaling-receptor and phosphatidylinositol binding, and is associated with breast and lung cancer." (PMID 38409266, 2024). "Even though the vast majority of our hits are known essential genes in human cancer cell lines or human iPSC-derived neurons, this method reveals some unique hits that have not been previously reported, including Jtb, Snx17, Psph, Bag1, and Becn1." (PMID 37398301, 2024).
cardiac diseases (1 paper, 2025). "Among these, SNX17 has been implicated in the pathogenesis of several diseases, including cardiac diseases 16,32 and neurological disorders 17,33." (PMID 40303303, 2025).
tumor (1 paper, 2025). "In this study, we found that overexpression of SNX17 significantly promoted the tumor growth in immunocompetent C57BL/6 mice." (PMID 40303303, 2025). "Compared with the control group, overexpression of SNX17 in Huh7 cells accelerated tumor growth." (PMID 40303303, 2025). "Therefore, we speculate that SNX17 may influence the tumor suppressive microenvironment by regulating the infiltration of M2 macrophages, MDSCs, and Treg cells." (PMID 40303303, 2025). "In addition, overexpression of SNX17 in Hepa1-6 mouse HCC syngeneic model promoted tumor growth." (PMID 40303303, 2025). "Therefore, we speculate that SNX17 may affect the tumor microenvironment (TME)." (PMID 40303303, 2025).
SNX17 also shares sentences with these, for which no sentence is quoted: Alcohol Use Disorders (1 paper); colorectal cancer (1); endometriosis (1); myasthenia gravis (1); neurodegenerative disease (1); neurological disorders (1); Obesity (1); schizophrenia (1).